STIM1 (stromal interaction molecule 1)
Diseases named in the same sentence as STIM1 in open-access papers (continued):
Sharing a sentence is not in itself a finding about the gene and the disease.
tumor (continued). "Functional enrichment analysis of the top-ranked genes from each cell type allowed us to define the cell-specific roles of STIM1 expression in the tumor microenvironment." (PMID 33859736, 2021). "Together with other investigations dissecting the functional roles of SOCE in vascular endothelial cells, it is suggested that STIM1-mediated Ca2+ machinery can be an attractive therapeutic target for strategies against tumor neovascularization." (PMID 35008759, 2021). "Further evidence from the overexpression or silencing of STIM1 and Orai1 supported that in vivo anti-tumor effects of SKF-96365 or 2-APB involve the blockade of STIM1/Orai1 complex." (PMID 35008759, 2021). "Although association analysis can't determine causality, the results at least indicated a functional role of STIM1-mediated modulation in cell-cell interactions within the tumor microenvironment (TME)." (PMID 33859736, 2021). "These imply that STIM1 is associated with tumor growth and invasion, whereas STIM2 is mainly correlated with tumor growth." (PMID 35008759, 2021). "The malignant-cell-derived STIM1 scores for the bulky tumor data were computed by simply taking an average across the top 100 SCGs derived from the malignant single-cell data." (PMID 33859736, 2021). "This experiment shows that also in an in vivo setting, STIM1-KD cells were unable to proliferate and form a tumor." (PMID 34155535, 2021). "Consistently, STIM1 expression was substantially decreased in hyperplasia and tumor tissue at histological grade 3 and 4, compared to normal tissue." (PMID 34069353, 2021). "Being involved in store-operated calcium entry, both ORAI1 and STIM1, are essential for breast tumor cell migration and tumor metastasis." (PMID 34988012, 2021). "Our previous study has shown CTSS inhibition reduced Ca2+ influx through affecting SOCE activation and interfering STIM1 trafficking, which leads to the suppression of tumor cell progression." (PMID 33754020, 2021). "In glial cells, isolated from tumor biopsies, the level of Orai1 expression is upregulated, while the level of STIM1 seems to be comparable to healthy cells." (PMID 33333945, 2020). "In an early study Yang and colleagues showed that the expression of STIM1 is higher in HCC tumor tissue than in paired non-tumor liver tissue." (PMID 32987945, 2020). "Unexpectedly, our data showed that STIM1 was downregulated in the invading-edge in comparison with the corresponding tumor tissue of HCC, which correlated with PVTT formation and poor prognosis of HCC patients." (PMID 32483465, 2020). "We previously reported that STIM1 is upregulated during tumor growth and correlates with elevated hypoxia-inducible factor-1 alpha (HIF-1α) in hypoxic HCC." (PMID 32483465, 2020). "In studies on GBM human U251 and rat C6 cells, STIM-1 knockdown has been shown to reduce Ca2+ influx and to inhibit tumour cell proliferation and induce apoptosis." (PMID 32098295, 2020). "For example, STIM1 is over-expressed in colorectal cancer and its expression level is positively correlated with tumor size, depth of invasion, and lymph node metastasis." (PMID 32599788, 2020). "Using immunohistochemical analysis, high KCa3.1 expression in PDAC tissue was correlated with TNM stages III and IV, and high expression of STIM1 was correlated with tumor grade." (PMID 33178018, 2020). "Compared with PVTT negative group, the samples from HCC patients with PVTT showed lower expression of STIM1 in the tumor invading-edge." (PMID 32483465, 2020). "In alveolar epithelial cells, STIM1 silencing attenuates the tumor growth, arresting cells in G1 phase in a p21 and cyclin D1-mediated pathway." (PMID 32733237, 2020). "In the same direction, STIM1 siRNA inhibits the migration and invasion abilities of the highly invasive tumor hepatic cells." (PMID 32733237, 2020).
tumor (continued). "We performed qRT-PCR, intracellular Ca2+ monitoring, protein analyses, and real-time cell proliferation assays on EpCAM(+)CD133(+) subpopulation of tumor-initiating Huh-7 HCC cells expressing high levels of STIM1 and/or Orai1." (PMID 31366337, 2019). "Results from the simultaneous immunostaining of STIM1 and STIM2 showed that, despite the overexpression of both isoforms in tumor tissues, STIM1 is the principle ER Ca2+-sensing molecule detected in the invasive tumor front." (PMID 31252656, 2019). "Next, it was further observed that a pool of STIM1 present in the plasma membrane characterizes tumor progression and controls constitutive Ca2+ entry." (PMID 31014395, 2019). "Further studies would contribute to the understandings of the clinical implications of such patterns of STIM1/STIM2 expression and the grades of STIM1 distribution in the invasive tumor front." (PMID 31252656, 2019). "On gross inspection, the tumor xenografts formed by STIM1-shRNA-infected A549 cells were markedly smaller compared with those formed by A549 or Scr-shRNA-infected A549 cells." (PMID 31564210, 2019). "These imply that STIM1 is associated with both tumor growth and invasion, whereas STIM2 is mainly correlated with tumor growth." (PMID 31252656, 2019). "STIM1 was initially identified as a tumor suppressor gene in human rhabdoid tumor and rhabdomyosarcoma cell lines." (PMID 31252656, 2019). "The roles of STIM1 and Orai1 in carcinogenesis, tumor initiation, proliferation and metastasis have recently attracted significant attention." (PMID 31366337, 2019). "Compared with tumor xenografts in mice implanted with A549 or Scr-shRNA-infected A549 cells, the tumor xenografts grew significantly slower following implantation of A549 STIM1-shRNA-infected cells." (PMID 31564210, 2019). "Stim1 protein was upregulated in CRC tissues as compared to adjacent non-tumor tissues, whereas Stim2 transcripts were over-expressed in a well annotated cohort of CRC patients treated with adjuvant 5-FU chemotherapy." (PMID 30123430, 2018). "In comparison to control cells, STIM1 knockdown tumor cells had reduced capacity to colonize organs such as spleen and kidneys." (PMID 30373149, 2018). "The strict requirement of Stim1 for tumor vascularization is further suggested by the recent finding that Stim1 transcription in hypoxic tumors is finely regulated by HIF-1." (PMID 29324706, 2018). "In conclusion, this study demonstrated that overexpression of STIM1 in HNSCC tissue has significant influence on tumor cell growth and apoptosis in vitro and in vivo." (PMID 28494008, 2017). "Tumor size and weight in nude mice was substantially inhibited in STIM1-siRNA group compared with the control group in vivo." (PMID 28494008, 2017). "On the other hand, 92% of cases showed intermediate or high grade of STIM1 expression in the paired tumor tissues (P < 0.001, compared to the intensity grades for STIM1 expression in non-cancerous cervix)." (PMID 28912430, 2017). "In this regard, the larger SOCE observed in tumor cells and increased expression of associated molecular players as Orai1, TRPC1 and Stim1, likely allows formation of larger Ca2+ domains near mitochondria." (PMID 28903423, 2017). "IHC results showed that STIM1 expression levels in tongue and epiglotic tumor tissues were higher compared with that of adjacent normal tissue." (PMID 28494008, 2017). "The composite molecules of SOCE; i.e., Orai1 and STIM1 suggest a poor outcome for GC by advancing tumor cell proliferation, metabolism, migration, and invasion through targeting metastasis-associated in colon cancer-1 (MACC1)." (PMID 28264681, 2017). "Overexpression of STIM1 in tumor tissue was closely related to tumor size (linear fit, R = 0.9034, p< 0.001) but not to neck lymph node metastasis." (PMID 28494008, 2017). "Several studies have demonstrated that STIM1-mediated SOCE dysregulation is involved in tumor development and progression." (PMID 28494008, 2017).
tumor (continued). "Silencing STIM1 inhibited the proliferation and colony formation of A549 cells in in vitro experiments, attenuated the growth of tumor xenografts of A549 cells in in vivo experiments and induced the arrest of cell cycle in the G1 phase." (PMID 27863410, 2016). "STIM1 was initially suggested to be a tumor suppressor given that it induced the inhibition of rhabdoid tumor and rhabdomyosarcoma cell lines." (PMID 27863410, 2016). "We also investigated the influences of STIM1 silencing on the proliferation and tumor formation of A549 cells in in vitro and in vivo experiments, and the distribution of cell cycle of A549 cells." (PMID 27863410, 2016). "It should be mentioned that STIM1 was reported to be overexpressed in tumor tissues from subjects with early-stage cervical cancer." (PMID 25481035, 2015). "Although STIM1 levels were decreased in hyperplasia and tumor patients, this protein was expressed at significantly higher levels in tumors at low histological grade than in hyperplasia tissues." (PMID 26257076, 2015). "It is known that STIM1-mediated Ca2+ oscillation controls invadopodium formation and focal adhesion turnover, and ultimately orchestrates tumor cell invasion and migration." (PMID 26543234, 2015). "Specifically, the enriched BP terms provided support for the involvement of STIM1 and STIM1-related molecular signatures in tumor invasion progress." (PMID 26543234, 2015). "To elucidate the function of SOCE in modulating the TME and tumor-associated macrophages (TAM, M2 phenotype), we tested the effect of STIM1 and ORAI1 on recruitment U937, a human leukemic monocyte macrophage cell line, in both DU145 and PC3 cells." (PMID 26257076, 2015). "hsa-miR-18a, that targets CDC42 and acts as a tumor suppressor, was significantly downregulated in STIM1-enriched patients." (PMID 26543234, 2015). "Mouse models have shown that STIM1 and Orai1 expression is critical for breast cell tumour migration and metastasis." (PMID 24000152, 2013). "Through U251 xenograft model in nude mice, we found that STIM1 silencing also significantly affect tumor growth in vivo." (PMID 23578185, 2013). "We found that SOCE in T cells curtails the growth of tumour allografts and that STIM1 and STIM2 deficient CTLs fail to prevent tumour cell engraftment." (PMID 23922331, 2013). "The results from these studies demonstrate the crucial role of STIM1-mediated Ca2+ influx in aggravating tumor development in vivo, especially in tumor angiogenesis and metastasis." (PMID 23594099, 2013). "The role of ORAI1/STIM1 complex has been studied recently also in EC migration and tumor vascularization." (PMID 24204345, 2013). "STIM1/SOX2 expression in tumor cells, as well as microenvironment cells, could contribute to PDAC and AAC tumorigenesis." (PMID 38532463, 2024). "STIM1 may be involved in a wide range of biological functions in non-tumor cells, including immunological cells, endothelial cells, and fibroblasts." (PMID 38532463, 2024). "Our findings that degradation of STIM1 through FAM134B-mediated ER-phagy is involved in cell proliferation might help to explain the role of FAM134B as a tumor suppressor." (PMID 39128711, 2024). "In addition to FAM134B, STIM1 is both an oncogene and a tumor suppressor according to the tumor types." (PMID 39128711, 2024). "Furthermore, based on the term “stromal interaction molecule” of STIM1, we proposed a possible function for its expression in the tumor microenvironment cells." (PMID 38532463, 2024). "Recent studies have shown that calcium signaling can alter the levels of these PCDs in tumor cells, but whether STIM1 is involved requires further investigation." (PMID 37932320, 2023). "Therefore, the molecular mechanisms of STIM1 regulation of apoptosis need to be investigated differentially for distinct tumor types." (PMID 37932320, 2023).
tumor (continued). "Further investigation into the mechanisms through which STIM1 controls other forms of tumor cell death could aid in the discovery of novel therapeutic targets." (PMID 37932320, 2023). "Furthermore, STIM1 contributes to resistance against antitumor therapy by influencing tumor cell death." (PMID 37932320, 2023). "Here, the tumor cell deaths regulated by STIM1 and their mechanisms are summarized." (PMID 37932320, 2023). "In several tumor types, enhanced proliferation correlates with ectopic STIM1/Orai1 expression." (PMID 36612099, 2022). "Interestingly, STIM1 is overexpressed in several types of tumours, and is therefore acknowledged to be a promoter of tumour migration and invasion, thus standing as an attractive target for controlling tumorigenesis." (PMID 35269437, 2022). "Moreover, studies have shown that high expression of STIM1 is significantly related to the tumor grade and early recurrence, which are important clinical factors affecting the prognosis of PDAC patients." (PMID 36187789, 2022). "In addition, transcriptomic analysis of glioblastoma tumor tissues showed overexpression of STIM1, ORAI1, and TRPC1." (PMID 35711942, 2022). "In a zebrafish xenograft model, STIM1-KD decreased tumor growth." (PMID 34155535, 2021). "Regulators of cellular Ca2+ homeostasis, including ORAI1 (Calcium Release-Activated Calcium Channel Protein 1), STIM1 (Stromal Interaction Molecule 1), and TRP (Transient Receptor Potential) channels, are implicated in tumor cell migration and an aggressive cell phenotype." (PMID 34988012, 2021). "Interestingly, before being implicated in SOCE, STIM1 was initially cloned as a candidate tumor suppressor gene on chromosome 11 region p15.5 and named GOK." (PMID 34069353, 2021). "Suppression of miR-145 in recipient HUVECs by miR-145 antagomir transfection abolished the anti-angiogenic effect of Exo-STIM1-KO in HUVECs, suggesting that miR-145 might play pivotal roles in the Exo-STIM1-KO attenuated tumor angiogenesis effect." (PMID 33414420, 2021). "Since such entry has been linked to stromal interaction molecule 1 (STIM1), we examined whether the virus acts via STIM1-dependent Ca2+ signaling to promote tumor angiogenesis in NPC." (PMID 34684224, 2021). "Furthermore, several different tumor types have shown a positive correlation between STIM1 and HIF1a levels." (PMID 33919156, 2021). "For this reason, tumor cells harboring an amplification of STIM1 may be able to thrive under hypoxic conditions by activating HIF1a through SOCE, circumventing the dampened ER stress response and ATF4-dependent HIF1a activation." (PMID 33919156, 2021). "For example, the inhibition of SOCE by genetic deletion of ORAI1, STIM1, or STIM2 in murine CD4+ T cells impaired Th17 cell function, causing a decrease in the production of IL-17, which is believed to be proinflammatory factor important for tumor progression." (PMID 34122115, 2021). "However, we found that STIM1 was notably downregulated in the tumor invading-edge (the region between tumor and para-tumor), compared with the corresponding tumor region of the HCC tissue." (PMID 32483465, 2020). "Although STIM1-mediated SOCE is essential for the migration of various cell types, including tumor cells 13-15, the role of STIM1 in dynamic HCC progression, especially in metastatic HCC cells, remains unclear." (PMID 32483465, 2020). "Furthermore, in breast cancer cell line MDA-MB-231, STIM1 and Orai1 remodel focal adhesion turnovers and are required for tumor invasion and metastasis." (PMID 32599788, 2020). "During tumor growth, STIM1 stabilized Snail1 protein by activating the CaMKII/AKT/GSK-3β pathway." (PMID 32483465, 2020). "However, a number of other previous studies have suggested that the STIM1 gene acts as a tumor suppressor." (PMID 31564210, 2019). "These highlight the clinical significance of STIM1 and Orai1 in tumor progression." (PMID 31252656, 2019).
tumor (continued). "In addition, a significant reduction in the wet weight of tumors from STIM1-shRNA-infected tumor cell xenografts compared with the controls was observed." (PMID 31564210, 2019). "The most extensively examined molecules of SOCE in tumor biology are STIM1 and Orai1." (PMID 31252656, 2019). "Furthermore, knockdown of STIM1 in NSCLC cells significantly reduced the levels of xenograft tumor growth in nude mice." (PMID 31564210, 2019). "Therefore, STIM1/Orai1-mediated Ca2+ machinery is a potential molecular target for strategies against tumor neovascularization." (PMID 31252656, 2019). "Moreover, the expression of TRPC1, ORAI1, ORAI2, ORAI3 and STIM1 was increased in tumor cells in contrary to STIM2 protein which was found to be depleted." (PMID 31010205, 2019). "Functional assays revealed that mCRC cell proliferation and migration are not affected in Stim1-, Orai1- and Orai3-deficient cells, thereby confirming that Stim and Orai proteins do not mediate tumor growth and metastases in patients-derived CRC cells." (PMID 30123430, 2018). "In addition, Orai1 and STIM1 are crucial for breast cancer cell migration in vitro and tumor metastasis in vivo." (PMID 28264681, 2017). "Orai1 and STIM1 have been shown to be highly expressed in tumor cells, and may contribute to malignant biological behaviors." (PMID 28264681, 2017). "Abnormal overexpression of STIM1 contributed to large tumor sizes and low 5-year survival rates." (PMID 27013185, 2016). "Combined with previous results, silencing STIM1 inhibited the growth of many types of tumor cells." (PMID 27863410, 2016). "STIM1 was detected to be expressed at significantly lower levels in hyperplasia and tumor tissues at histological grade 3–4 than in normal tissues, indicating that these molecules might have an inhibitory role in human prostate tumorigenesis." (PMID 26257076, 2015). "Curiously, a recent investigation conducted on primary cultures established from GBM disclosed that Stim1/Orai1 account for ~20% of cell growth, thereby confirming that freshly isolated tumour cells may become independent on SOCE to proliferate." (PMID 25126575, 2014). "Moreover, STIM1-dependent Ca2+ signaling plays an important role in tumor growth and angiogenesis in vivo." (PMID 23594099, 2013). "Observations of increased growth arrest and apoptosis in some mammalian cell lines overexpressing STIM1 led to the initial hypothesis that STIM1 functions as a tumour suppressor." (PMID 18950512, 2008). "However, one note of caution must be added in that STIM1 was initially identified as a candidate tumour suppressor gene and the consequences therefore of long term inhibition of STIM1 expression need to be explored further." (PMID 16987424, 2006). "Moreover, STIM1 has the ability to regulate immune cells within the tumor microenvironment." (PMID 37932320, 2023). "Therefore, the use of the STIM1/STIM2 ratio as a marker of tumor aggressiveness might be promising and worth further evaluated." (PMID 31252656, 2019). "Thus, the down-expression of STIM1 or Orai1 could impair cell migration and/or intralymphatic spread, promoting homing of tumor B cells to extra-nodal sites." (PMID 30373149, 2018). "Thus, this study mainly focuses on STIM1 function in HNSCC tumor growth." (PMID 28494008, 2017). "Furthermore, TSCCA cell xenograft models confirmed that STIM1 could promote HNSCC tumor growth in vivo." (PMID 28494008, 2017). "However, the study from our group and the Korean group showed that the expression of STIM1 in tumor tissues remained unchanged or was even reduced as compared to that in neighboring normal tissues based on real-time RT-PCR, Western blot and immunohistochemistry assays." (PMID 25481035, 2015). "Thus, more work needs to be done to fully determine the role of STIM1 in tumorigenesis which might vary in different tumor types." (PMID 23578185, 2013).